FASN (fatty acid synthase)
Diseases named in the same sentence as FASN in open-access papers (continued):
Sharing a sentence is not in itself a finding about the gene and the disease.
colorectal cancer (continued). "For instance, nuclear Fusarium species have been demonstrated to induce FASN expression, a critical enzyme in colorectal cancer cell lipid biosynthesis." (PMID 41031610, 2025). "FASN is frequently overexpressed and/or activated in many cancers, including breast and colorectal cancers, which promotes fatty acid synthesis and cancer progression." (PMID 39971971, 2025). "The fatty acid synthase (FASN), an enzyme involved in de novo fatty acid synthesis, is overexpressed in many cancers, including colorectal cancer." (PMID 39860065, 2025). "Based on previous studies, we aimed to assess the expression of FASN in colorectal cancer tissues, adjacent tissues, and healthy tissues by immunohistochemistry." (PMID 40995612, 2025). "The aberrant expression of FASN promotes the synthesis of new fatty acids, effectively regulating the tumor microenvironment of colorectal cancer cells." (PMID 40936898, 2025). "A recent published study also reported the lipid-rich microenvironment activates palmitate biosynthesis in metastatic colorectal cancer cells by up-regulating FASN." (PMID 38415253, 2024). "Accordingly, FASN activity has been reported to regulate FAO in colorectal cancer, promoting the oxidation of endogenous FAs to produce ATP." (PMID 36753044, 2023). "Upregulation of FASN has been found to accompany many human cancers’ natural history and is related to a poor prognosis, including bladder cancer, colorectal cancer, and pancreatic cancer." (PMID 37587470, 2023). "Although our study highlighted that FASN enhanced oxaliplatin resistance in colorectal cancer cells, it still had some limitations." (PMID 36765520, 2023). "First, as both the composition of fatty acid and tumorigenesis of colorectal cancer are closely related to diet patterns, further investigation of the relationship between dietary patterns and FASN, as well as the response of chemotherapy, are warranted." (PMID 36765520, 2023). "The culture of human lung microvascular endothelial cells in a medium conditioned from FASN knockdown colorectal cancer cells decreased VEGFR-2 activation, cell proliferation, migration and tubulogenesis." (PMID 36934087, 2023). "Orlistat, an inhibitor of the thioesterase domain of FASN, was administered to colorectal cancer cell lines." (PMID 36765520, 2023). "In conclusion, our study depicts the relationship between FASN expression and colorectal cancer prognosis and oxaliplatin resistance." (PMID 36765520, 2023). "To explore the mechanistic function of fatty acid biosynthesis, especially that of FASN, in colorectal cancer progression, we analyzed the expression of multiple genes from the GEO database (GSE195860, GSE28702, and GSE69657)." (PMID 36765520, 2023). "Together, these results suggest that FASN is stabilized by USP22 in colorectal cancer, and the dysregulated USP22/FASN axis is a important driver for tumorigenesis." (PMID 36333288, 2022). "Even though we did not see significant changes in CS mRNA expression between normal mucosa and tumor tissues, the TCGA data demonstrate a significant correlation between the expression of CS and FASN in human colorectal cancer." (PMID 35742953, 2022). "Overexpression of Fatty Acid Synthase (FASN) correlates with poor prognosis in colorectal cancer (CRC)." (PMID 35742953, 2022). "CAF-induced colorectal cancer cell migration is abolished by FASN knockdown or by reducing the uptake of fatty acids in vitro and in vivo." (PMID 36115986, 2022). "Given that in the mouse model of inflammation-driven colorectal cancer, an inverse expression of Hakai and FASN expression was detected, we decided to analyse the expression of Hakai and FASN in human inflammatory colon disorders, including UC and CD." (PMID 36266428, 2022).
colorectal cancer (continued). "For example, fatty acid synthase (FASN) generates fatty acids from malonyl-CoA and acetyl-CoA via de novo FA synthesis and is upregulated in colorectal cancer." (PMID 35954376, 2022). "According to previous reports, FASN inhibition can reduce the proliferation and migration of colorectal cancer cells by suppressing the activity of the “HER2-PI3K/Akt axis”." (PMID 35566090, 2022). "These FASN-targeted agents were confirmed to reduce tumor proliferation and induce cell cycle arrest in breast and colorectal cancers." (PMID 36428733, 2022). "While in colorectal cancer FASN enzyme function was permanently blocked for more than 6 days or the protein was irreversibly knocked-down, in OC both enzyme function and protein levels were transiently reduced for a maximum of 72 hours." (PMID 33928023, 2021). "FASN has been shown to play a role in tumor invasion and metastasis, and FASN inhibition or knockdown reduced liver metastasis of colorectal cancer." (PMID 34150624, 2021). "FASN knockdown resulted in reduced colorectal cancer cell proliferation and migration, while FASN overexpression exhibited the reverse phenomenon." (PMID 34421595, 2021). "The high expression of FASN in colorectal cancer tissues was correlated with lymph node metastasis, the Tumor, Node, Metastases (TNM) stage and poor prognosis in colorectal cancer patients." (PMID 34421595, 2021). "For example, we found miR-92a-3p, a member of the miR-17/92-cluster that has previously been associated with prognosis, metastasis and response to chemoradiotherapy in colorectal cancer, and the predicted target gene FASN." (PMID 33255413, 2020). "FASN hyperactivation in colorectal cancer cells leads to lipid droplets accumulation, increased FAO and reliability on aerobic glycolysis, suggesting the dependence of tumor cells on stored lipid forms for energy homeostasis." (PMID 32670883, 2020). "Fatty acids synthase (FASN), a crucial enzyme in fatty acids synthesis, was found to be significantly increased in CAFs, whereas CAF migration was blocked by knockdown of FASN in colorectal cancer." (PMID 33374292, 2020). "In colorectal cancer cell lines, suppression of FASN expression is shown to impair glycolytic capacity and reserves of HT29 and HCT116 cells." (PMID 32872164, 2020). "In an in vitro colorectal cancer model, FASN inhibition is shown to lower mitochondrial respiration and FAO." (PMID 32872164, 2020). "In human, CRNDE knockdown by siRNA in colorectal cancer cell lines leads to an under-expression of FASN, and an overexpression of ACADVL and ACOT9, two genes involved in lipid catabolism." (PMID 31752679, 2019). "In colorectal cancer cells, stable knock-down of FASN led to a significant decrease in glycolytic capacity." (PMID 29331414, 2018). "Fatty Acid Synthase (FASN), a key enzyme of de novo lipogenesis, is upregulated in many cancers including colorectal cancer (CRC); increased FASN expression is associated with poor prognosis." (PMID 29872506, 2018). "We found that expression of fatty acid synthase was elevated, while the expression of fatty acid transporters was reduced in colorectal cancer." (PMID 28938608, 2017). "While, the decreased levels of lipogenic enzymes Lipoprotein lipase (LPL) and Fatty acid synthase (FAS), important components of the regulation of lipolysis in adipocytes pathway was reported to be associated with colorectal cancer." (PMID 28587194, 2017). "Fatty acid synthase (FASN), a key enzyme of de novo lipid biosynthesis, is significantly unregulated in many cancers, including colorectal cancer (CRC), and is associated with aggressive disease and a poor prognosis." (PMID 25970773, 2015). "In this study, we observed that RNAi of FASN expression blocked the proliferation and migration of colorectal cancer cells and increased apoptosis rate." (PMID 23725225, 2013). "And the influence of FASN on proliferation and migration of colorectal cancer cells was also explored." (PMID 23725225, 2013).
colorectal cancer (continued). "It implies that FASN plays a central role in the malignant phenotype maintenance of colorectal cancer cells by enhancing cancer cell survival and proliferation." (PMID 23725225, 2013). "It implies that FASN can effectively regulate the “HER2-PI3K/Akt axis” activity of colorectal cancer cells." (PMID 23725225, 2013). "We also discuss the effects of FASN in patients with colorectal cancer." (PMID 40995612, 2025). "The underlying mechanisms of how FASN promotes colorectal cancer development have not yet been investigated." (PMID 40995612, 2025). "This research aimed to explore the expression and role of FASN in colorectal cancer." (PMID 40995612, 2025). "Fatty acid synthase (FASN) is a key regulator of lipid metabolism, but its role in colorectal cancer (CRC) stemness and ferroptosis remains unclear." (PMID 40901481, 2025). "In addition to regulating fatty acid metabolism, FASN can maintain glycolysis and the tricarboxylic acid cycle in colorectal cancer." (PMID 40995612, 2025). "Consequently, this interaction elevates the expression of SREBP-1 and its downstream target gene FASN, thereby promoting lipid accumulation in colorectal cancer (CRC)." (PMID 38272906, 2024). "Reportedly, chemoresistance of colorectal cancer cells was produced by LPCAT2-mediated lipid droplet formation, which was also aided by prothymosin α, and metastasis-associated in colon cancer through SREBP-1- and FASN-mediated lipogenesis respectively." (PMID 37584712, 2023). "Increasing evidence showed that FASN also contributes to colorectal cancer cell metastasis." (PMID 35350838, 2022). "Given the previous results showing that Hakai expression in AOM-DSS model of CAC was decreased in inflammatory conditions compared to tumour tissue of colitis-associated colorectal cancer (AOM DSS/Tumour) and healthy tissues, we extended our results to analyse FASN expression in this mouse model." (PMID 36266428, 2022). "Moreover, a potential mechanism through FASN-induced colorectal cancer proliferation and metastasis upon its regulation of the AMPK/mTOR pathway by increasing ATP production, resulted in inhibition of AMPK and activation of mTOR has been demostrated." (PMID 34421595, 2021). "In addition, the up-regulation of FASN enhances colorectal cancer cell proliferation and metastasis." (PMID 34421595, 2021). "A high serum FASN level is a prognosis marker of late stage colorectal cancer patients." (PMID 33925358, 2021). "Furthermore, FASN knockdown resulted in reduced colorectal cancer cell proliferation and migration while FASN overexpression had the opposite effects on colorectal cancer cells." (PMID 34421595, 2021). "FASN inhibition has been shown to induced ER stress in HT-29, a colorectal cancer cell line." (PMID 32872164, 2020). "Likewise, treatment of colorectal cancer with a different FASN inhibitor, TVB-3166, showed similar observations." (PMID 32872164, 2020). "In addition, a significant correlation between the expression of FASN and SphK2 at mRNA and protein level was detected in primary colorectal cancer." (PMID 32456134, 2020). "The novel fatty acid synthase inhibitor, TVB-3664, shows anti-cancer activity in multiple cancers including colorectal cancer; however, it is unclear whether uptake of exogeneous fatty acids can compensate for the effect of fatty acid synthase inhibition." (PMID 32850342, 2020). "Preclinical evaluation of novel FASN inhibitors in primary colorectal cancer cells (CRCs) and a patient-derived xenograft model of colorectal cancer showed that anti-tumor activity was primary due to a significant decrease in the activation of Akt and Erk1/2 oncogenic pathways in CRCs." (PMID 30717356, 2019). "Of note, ML364 administration caused cell cycle arrest in colorectal cancer and lymphoma cell lines, although the specific effect of the drug on FASN levels was not investigated." (PMID 31921669, 2019). "Fatty acid synthase (FASN), a lipogenic enzyme, is upregulated in colorectal cancer (CRC)." (PMID 25970773, 2015).
colorectal cancer (continued). "However, the relationship between FASN-mediated lipid reprogramming and the immune response in colorectal cancer (CRC) remains unclear." (PMID 40148316, 2025). "Hence, our results suggest that FASN may play an essential role in colorectal cancer and may be an attractive therapeutic target in the future." (PMID 40995612, 2025). "Given that TALIN-1, MRE11, and CCT8 interact with E-cadherin, that FASN, FLNA, and DDX3X are implicated in EMT, and that FKBP4 expression is upregulated in colon cancers, we examined E-cadherin expression in human colorectal carcinoma HCT116 cells under the FKBP4 knockdown." (PMID 41203126, 2025). "Reportedly, chemoresistance of colorectal cancer cells was produced by LPCAT2-mediated lipid droplet formation, which was also aided by prothymosin α,25 and metastasis-associated in colon cancer 126 through SREBP-1- and FASN-mediated and lipogenesis respectively." (PMID 38241178, 2024). "A recent study reported that overexpression of FASN was linked to a worse survival outcome in patients with colorectal cancer, which indicates that FASN-mediated fatty acid synthase and metabolism play a negative role and contribute to the poor prognosis of cancers." (PMID 36428733, 2022). "There are reports supporting increased FASN activity and expression in various human cancers such as breast cancer, thyroid cancer, ovarian cancer, prostate cancer, oral cancer, colorectal cancer, endometrial metastatic cancer and in mesothelioma, renal cancer, and retinoblastoma." (PMID 32670883, 2020). "Furthermore, the decreased proliferation and migration of colorectal cancer cells could be partly attributed to the decreased activity of “HER2-PI3K/Akt axis” what was regulated by FASN." (PMID 23725225, 2013). "However, the function and significance of FASN in colorectal cancer remain unclear." (PMID 40995612, 2025). "For example, in colorectal cancer, long-chain non-coding RNA POU6F2-AS1 promotes the expression of YBX1 by directly binding to it, and YBX1, in turn, binds to the promoter region of FASN to activate its transcription." (PMID 40936898, 2025). "Overexpression of fatty acid synthase (FASN), a key enzyme in fatty acid synthesis, correlates with GFPT1 upregulation and enhanced colorectal cancer proliferation." (PMID 40830088, 2025). "The FASN inhibitor orlistat inhibits EGFR palmitoylation and inhibits the stem cell properties of colorectal cancer (CRC) cells." (PMID 38415253, 2024). "To investigate the key role of PITPNC1/FASN/CD155 in immune regulation, we individually knocked down PITPNC1 and FASN and knocked down PITPNC1 while overexpressing FASN in radioresistant colorectal cancer cell lines." (PMID 38291470, 2024). "Next, we utilized the TIMER2.0 database to analyze the correlation between the expression of the FASN and CD155 genes in colorectal cancer tissues, revealing a significant positive correlation." (PMID 38291470, 2024). "The expression of fatty acid synthase (FASN) is elevated in multiple cancers, including colorectal cancer." (PMID 36765520, 2023). "The reprogramming of lipid metabolism has been highlighted in colorectal cancer (CRC) studies, suggesting a critical role for the scavenger receptor CD36 and fatty acid synthase (FASN) in this malignancy." (PMID 36556492, 2022). "FASN positively upregulated the AMPK/mTOR pathway and enhanced proliferation in colorectal cancer cells." (PMID 35742944, 2022). "Similar to cancer cells, CAFs in colorectal cancer undergo lipid metabolism, which symbolizes more fatty acid accumulation resulting from CAF FASN upregulation." (PMID 36115986, 2022). "Accordingly, a very recent report demonstrated that inhibition of FASN upregulated the lipid receptor CD36 and stimulated the uptake of a lipophilic fluorochrome in colorectal cancer cells." (PMID 33928023, 2021).
colorectal cancer (continued). "More recently, a study on the next-generation inhibitors of FASN, TVB-3166, and TVB-2640, has shown their antitumor efficacy in models of breast and colorectal cancer." (PMID 32422889, 2020). "In a panel of colorectal cancer cell lines and primary colorectal cancer cells, TVB-3166 has shown a promising anti-tumor response that correlates with reduced FASN levels." (PMID 32872164, 2020). "Again, the scarce literature only mentions a fatty acid synthase increased expression in both DSS-induced colitis mucosa and colorectal cancer and our work only focused on the systemic blood serum metabolome." (PMID 29867918, 2018). "In the current study, we demonstrated that RNAi-mediated inhibition of FASN dramatically reduced the expression of HER2, PI3K and Akt in colorectal cancer cells." (PMID 23725225, 2013). "A downregulation of FASN effectively inhibits the activity of “HER2-PI3K/Akt axis” and alters the malignant phenotype in colorectal cancer cells." (PMID 23725225, 2013). "In this study, our aims were to explore the role of FASN in regulating the “HER2-PI3K/Akt axis” activity and malignant phenotype of colorectal cancer." (PMID 23725225, 2013). "Considering that HER2 overexpression stimulates the activity of FASN and ultimately mediates increased endogenous fatty acid biosynthesis, these findings implies a bidirectional connection between FASN and HER2 in colorectal cancer cells." (PMID 23725225, 2013). "Studies have demonstrated that, compared to normal fibroblasts, CAFs overexpress fatty acid synthase (FASN), increasing the uptake and metabolism of fatty acids and phospholipids, and releasing lipid metabolites that promote the growth of colorectal cancer cells." (PMID 39769177, 2024). "Hypoxia also promotes the acetate uptake and hypoxia-inducible factor 1 (HIF-1) activation in colorectal cancer cells, which induces the sterol regulatory-element binding protein-1 (SREBP-1) and fatty acid synthase (FASN) overexpression, enzymes involved in de novo lipid synthesis." (PMID 37760840, 2023). "Importantly, metastatic liver cancer samples from CRC patients demonstrated higher levels of FASN and CSN6 when compared with colorectal cancer of primary site and its adjacent normal tissue, indicating the role of CSN6/FASN in promoting metastasis." (PMID 37202390, 2023). "The inhibition of FASN with the compound orlistate impairs melanoma-induced metastases and angiogenesis in mice, and the silencing of FASN attenuates CD44 expression-induced signaling and metastasis formation in colorectal cancer mouse models." (PMID 36980201, 2023). "In addition, FASN overexpression is correlated with lymph node metastasis, TNM stage and a poor prognosis in colorectal cancer patients." (PMID 34421595, 2021). "Finally, a recent study indicates that lipids secreted by CAFs are taken up by colorectal cancer (CRC) cells and that deletion of the fatty acid synthase (FASN) or the inhibition of FA uptake in CAFs reduced CRC cell migration." (PMID 33540679, 2021). "Hence, in this study, we analyzed the potential link between FASN and the activity of “HER2-PI3K/Akt axis” in colorectal cancer cells." (PMID 23725225, 2013). "This concept is also supported by the observation that overexpression of FASN is correlated with high degree of microsatellite instability in colorectal cancer independent of CpG island methylator phenotypes." (PMID 18523653, 2008). "In addition, co-culture experiments and in vivo tumor-bearing experiments have shown that silencing PITPNC1 can inhibit FASN/CD155, enhance CD8+ T cell immune function, promote colorectal cancer cell death, and ultimately reduce radioresistance in tumor-bearing models." (PMID 38291470, 2024).